SP1 (Sp1 transcription factor)
Diseases named in the same sentence as SP1 in open-access papers (continued):
Sharing a sentence is not in itself a finding about the gene and the disease.
ischemic disease (1 paper, 2024). Lack of blood supply to an area of the body, resulting in impairment of tissue oxygenation. "Previous studies have shown that mutations in STAT3 are associated with neurodegenerative diseases such as AD, whereas SP1 is associated with cardiovascular diseases, and NFkB is associated with hypoxic and ischemic disease." (PMID 39872979, 2024).
Kleefstra syndrome (1 paper, 2022). A genetic disorder characterized by intellectual disability, childhood hypotonia, severe expressive speech delay and a distinctive facial appearance with a spectrum of additional clinical features. "Here, we demonstrate that REST and SP1 interplay to co-ordinately regulate gene expression of a specific subset of genes associated with Kleefstra Syndrome." (PMID 35139903, 2022). "In addition, the study linked transcription factors REST and SP1 to disease specific changes relevant to Kleefstra Syndrome that portend pivotal cellular changes underpinning disease mechanism." (PMID 35139903, 2022). "This pipeline rapidly identified Kleefstra syndrome in genetic variant cells compared to healthy cells, and revealed novel findings potentially implicating the key transcription factors REST and SP1 in disease pathogenesis." (PMID 35139903, 2022). "In addition, transcription factors, REST and SP1, key to the etiology of Kleefstra syndrome were identified providing insight into disease mechanism which may facilitate the identification of drug targets for treatment." (PMID 35139903, 2022).
leukopenia (1 paper, 2017). "By integrating the regulatory relationships and functions among the gene sets of defense response, CEBPB, IRF protein family, and the transcription factor SP1, the etiopathogenesis of leukopenia can be explored more comprehensively." (PMID 28729650, 2017).
liposarcoma (1 paper, 2025). A usually painless malignant tumor that arises from adipose tissue. "Evidence from a G4-Chip-seq/RNA-seq analysis of liposarcoma cells and keratinocytes suggests that a folded G-quadruplex, and not just a GC-rich sequence alone, is the binding site for transcription factors such as AP-1 and SP1." (PMID 41158996, 2025).
lupus nephritis (1 paper, 2025). Glomerulonephritis in the context of systemic lupus erythematosus. "We observed a greatly increased expression of Sp1 in the kidney of lupus nephritis mice, and the elevated expression levels corelated with the severity of lupus nephritis." (PMID 40497974, 2025). "We wondered if upregulation of WDFY1 could be induced by the IL-6-driven upregulation of Sp1 expression in the kidney of lupus nephritis mice." (PMID 40497974, 2025).
malignant uterine tumors (1 paper, 2023). "Most importantly, TYMS, TK1, miR-26b-5p, and Sp1 panel should be further investigated as biomarkers of pathogenesis, prognosis, and differentiation of uLMS from other benign and malignant uterine tumors." (PMID 37373974, 2023).
memory impairment (1 paper, 2024). "ApoE4 Female: displays earlier onset of spatial and memory impairment, ↑ Aβ species, BACE1 and Sp1, and ↑ BACE1 expression." (PMID 39126053, 2024).
metabolic syndrome (1 paper, 2017). A cluster of metabolic risk factors for CARDIOVASCULAR DISEASES and TYPE 2 DIABETES MELLITUS. "If Sp1, Sp3, NF-kappaB, and VDR are increased in obese and T2D subjects, then this could be a mechanism underlying the elevated expression of ADAM19 in the metabolic syndrome." (PMID 28265178, 2017).
monocytic leukemia (1 paper, 2024). "The deletion or mutation of the CT element required for the binding of transcription factors SP1 and SP3 in the human lipoprotein LPL promoter led to a reduction of about 70–80% in promoter activity in a human monocytic leukemia cell line." (PMID 39590382, 2024).
motor neuron degeneration (1 paper, 2019). "Disruption of Sp1 or p11 also has neuroprotective effects in a traumatic model of motor neuron degeneration." (PMID 31439839, 2019).
mucoepidermoid carcinoma (1 paper, 2015). A carcinoma morphologically characterized the presence of cuboidal mucous cells, goblet-like mucous cells, squamoid cells, cystic changes, and a fibrotic stromal formation. "Inhibition of SP-1 by the curcumin analogue dibenzylideneacetone, led to increased expression of Bim and apoptosis in mucoepidermoid carcinomas, suggesting that SP-1 acts as a suppressor of Bim expression." (PMID 26405162, 2015).
myxoid liposarcoma (1 paper, 2021). A liposarcoma characterized by the presence of round non-lipogenic primitive mesenchymal cells and small signet ring lipoblasts within a myxoid stoma with a branching vascular pattern. "Relevantly, we previously showed that the inhibition of SP1 with the mithramycin analog EC-8042 was able to efficiently inhibit the growth of our myxoid liposarcoma model." (PMID 33806182, 2021).
periodontal disease (1 paper, 2021). "While increased Sp1 levels have been implicated as a factor in periodontal disease progression in previous studies, a thorough characterization of its role in PDL tissues has not been reported." (PMID 34255809, 2021).
periodontitis (1 paper, 2019). An acute or chronic inflammatory process that affects the tissues that surround and support the teeth. "The human homolog of this protein was not known, but recently, human common SP1 was identified in the saliva of patients with periodontitis at higher levels compared to healthy individuals." (PMID 30766890, 2019).
peritoneal cancer (1 paper, 2020). A peritoneum cancer that is located in the inside of the abdomen. "SP1 is a key regulator in mediating peritoneal cancer dissemination and niche-directed metastasis." (PMID 31659258, 2020).
Pleural effusion (1 paper, 2015). The presence of an excessive amount of fluid in the pleural cavity. "The African strain collection collated 109 isolates (108 from CSF, 1 from pleural effusion), 61 of them (56%) belonged to Sp1." (PMID 26214695, 2015).
psychosis (1 paper, 2022). "For AKT1, a differentially methylated region associated with a psychosis-related behavioral response overlaps with a binding motif for the well-known activating transcription factor, SP1, and a specific pattern of methylation may interfere with its binding." (PMID 35327363, 2022).
respiratory failure (1 paper, 2011). The significant impairment of gas exchange within the lungs resulting in hypoxia, hypercarbia, or both, to the extent that organ tissue perfusion is severely compromised. "The role of Sp1 in nociception is unstudied as null mice completely lacking Sp1 die early in embryogenesis, whereas, Sp3 -/- null mice are growth-retarded and die at birth due to respiratory failure." (PMID 21645329, 2011).
respiratory infection (1 paper, 2025). "The findings suggest that modulating the activity of TRAF1, USP7, and SP1 could provide a novel approach for managing this common and potentially severe respiratory infection in infants." (PMID 40121492, 2025).
retinitis (1 paper, 2022). Inflammation of the retina. "In contrast, only two of the three UL40 peptides, VMAPRTLIL (SP1) and VMAPRTLVL (SP3), were observed in the majority of intraocular fluid specimens from CMV-retinitis patients (in which one of the peptides was observed in each patient), and VVAPRTLIL (SP2) was not present in their ocular fluid." (PMID 36341392, 2022).
Right ventricular hypertrophy (1 paper, 2021). In this case the right ventricle is more muscular than normal, causing a characteristic boot-shaped (coeur-en-sabot) appearance as seen on anterior- posterior chest x-rays. "It has been reported that Sp1 levels are increased in right ventricular hypertrophy and in isoproterenol- or angiotensin II-stimulated cardiomyocytes." (PMID 34462460, 2021).
scoliosis (1 paper, 2019). A congenital or acquired spinal deformity characterized by lateral curvature of the spine. "No SP1 mutation association with scoliosis has yet been reported." (PMID 30598481, 2019).
Seizure (1 paper, 2022). A seizure is an intermittent abnormality of nervous system physiology characterized by a transient occurrence of signs and/or symptoms due to abnormal excessive or synchronous neuronal activity in the brain. "Seizures increase Sp1 activity, which is one of the upstream regulators for clasmatodendrosis." (PMID 36290607, 2022).
spinal cord ischemia (1 paper, 2020). Reduced blood flow to the spinal cord which is supplied by the anterior spinal artery and the paired posterior spinal arteries. "Prophylactic approaches for spinal cord protection are essential, and this is the first report demonstrating that the miR-128-3p/SP1 axis has critical functions in neuroprotection upon spinal cord ischemia." (PMID 33424542, 2020).
status epilepticus (1 paper, 2021). Status epilepticus is defined as a continuous seizure lasting more than 30 min, or two or more seizures without full recovery of consciousness between any of them. "Using the same intra-amygdala KA mouse model, P2X7R expression during status epilepticus also appears, however, to be controlled at the post-transcriptional level, involving the targeting of P2rx7 mRNA by microRNA-22, which is also under the control of Sp1." (PMID 34144123, 2021). "Following intra-amygdala KA induced status epilepticus in mice, P2X7R transcription seems to be under the control of the specificity protein 1 (Sp1) which is a member of the injury-activated transcription factor (IATF) family and highly expressed in the brain." (PMID 34144123, 2021).
T-cell acute lymphoblastic leukemia (1 paper, 2021). Acute lymphoblastic leukemia of T-cell origin. "We previously reported N-terminal IL-1α could bind to the promoter of specific protein 1 (SP1) and promoted the growth of human T-cell acute lymphoblastic leukemia cell line." (PMID 33430381, 2021).
T-cell leukemia (1 paper, 2021). A malignant disease of the T-lymphocytes in the bone marrow, thymus, and/or blood. "This was similar to Kuhlmann’s reported that in adult T-cell leukemia (ATL) patients, the human T-cell leukemia virus type 1 protein HTLV-1bZIP factor (HBZ) leaded to target gene activation by forming a heterodimer with Jund and interacting with SP1 in the hTERT promoter region." (PMID 34744749, 2021).
tauopathies (1 paper, 2017). "Finally, various neuronal pro-survival factors (Bcl-2, Bcl-x, and surviving) have been shown to be targets of SP1, suggesting the need for in-depth analysis of the role of SP1 in tauopathies." (PMID 28367114, 2017).
teratoma (1 paper, 2025). A non-seminomatous germ cell tumor characterized by the presence of various tissues which correspond to the different germinal layers (endoderm, mesoderm, and ectoderm). "POU5F1, CREB1, SP1-responsive transcriptome involved in RNA turnover, teratoma formation, and steroid synthesis were found to activated in cluster #4 cancers of the TCGA and GSE99420 cohorts." (PMID 40011822, 2025).
Thiamine deficiency (1 paper, 2021). Thiamine deficiency is a condition that occurs due to not enough thiamine (vitamin B1). "The different behavior of HPTEC and HMC on one side, and HPC and HGEC on the other, also was maintained as regards Sp1 expression, which was unchanged in the former, and upregulated by thiamine deficiency in the latter." (PMID 33916491, 2021).
Thrombocytopenia (1 paper, 2019). A reduction in the number of circulating thrombocytes. "Interestingly, megakaryocyte specific knockout of Sp1/Sp3 transcription factors display thrombocytopenia and platelet dysfunction in mice." (PMID 30894555, 2019).
thyroid nodule (1 paper, 2023). A small circumscribed mass in the THYROID GLAND that can be of neoplastic growth or non-neoplastic abnormality. "Furthermore, a bioinformatics approach points to the transcription factor Sp1 as being potentially involved in most of the alterations seen in the malignant thyroid nodules." (PMID 37833989, 2023).
tongue cancer (1 paper, 2024). A malignant neoplasm affecting the tongue. "In all patients and across various subgroups (tongue carcinoma, laryngeal and other types of carcinomas T2, T3, T4 status; age before and after 50 years; smoking and non-smoking), there are consistent differences in the methylation levels in the SP1 gene in tumor DNA compared to normal." (PMID 38540340, 2024).
type 1 diabetes (1 paper, 2024). "In a mouse model of STZ-induced type 1 diabetes, we demonstrated SP1 activation in glomerular podocytes by showing increased immunostaining of Thr453-phosphorylated SP1 in podocyte nucleus, which was reversed by treating the animals with i.p. injections of MIT." (PMID 38467599, 2024).
Uterine leiomyoma (1 paper, 2022). The presence of a leiomyoma of the uterus. "The inhibition of miR-29c expression in uterine leiomyoma is mediated by the transcriptional regulation of NF-kB and SP1." (PMID 35113040, 2022).
Zinc deficiency (1 paper, 2025). A deficiency of the essential metal Zinc; an essential cofactor for many enzymes. "Zinc deficiency impairs the DNA-binding activity of the transcription factor Sp1, leading to reduced expression of essential cell cycle regulators, e.g., cyclins and CDKS, ultimately causing cell cycle arrest." (PMID 41366814, 2025). "Since Sp1 binds to specific GC-rich sequences in the promoter regions of its target genes to activate their transcription, a reduction in its DNA-binding ability due to zinc deficiency can result in the downregulation of these target genes." (PMID 41366814, 2025). "Zinc deficiency can lead to a decrease in the DNA-binding ability of Sp1." (PMID 41366814, 2025).
cancer (638 papers, 2005 to 2026). A tumor composed of atypical neoplastic, often pleomorphic cells that invade other tissues. "Overexpression of SP1 frequently occurs in multiple cancers, including CRC, and is associated with poor prognosis." (PMID 39875519, 2025). "SP1 is a well-known member of the transcription factor family, which is implicated in plenty of essential biological processes and crucial in regulating cancer cell proliferation, apoptosis, ferroptosis, and drug resistance." (PMID 39927464, 2025). "Through in vivo and in vitro loss of function of SP1 in cancer cells, we revealed its role in driving cancer cell survival, invasive growth, and metastatic colonisation." (PMID 39748426, 2025). "AXL upregulation in cancer has been linked to transcription factors SP‐1 and MZF1, as well as STAT5 activation and hypoxia." (PMID 39395205, 2025). "SP1 is often overexpressed in many human cancers, and its expression levels are associated with tumor stage and poor prognosis." (PMID 40290118, 2025). "In vivo and in vitro loss-of-function studies of SP1 in cancer cells demonstrated its critical role in promoting cancer cell survival, invasive growth, and metastatic colonisation." (PMID 39748426, 2025). "GTSE1, which is highly expressed in various cancers, including PCa, and linked to poor prognoses, promotes PCa cell proliferation by activating the SP1/FOXM1 signaling pathway." (PMID 40626556, 2025). "Our focus narrowed to the SP1 transcription factor, which is overexpressed in various cancers, associated with poor prognosis, and constitutes a classical downstream feature in the AKT signalling pathway." (PMID 38279869, 2024). "SP1 is a promoter-specific binding factor that has been shown to be overexpressed in numerous cancers and is associated with poor prognosis." (PMID 38542784, 2024). "SP1 is associated with immunosuppression in several cancer types, including TNBC, and IL-1β is responsible for the activation of a pro-inflammatory pathway." (PMID 39576827, 2024). "Overall, inhibition and degradation of SP1 have been reported to be associated with the control of most SP1- and metabolic pathways-related cancers." (PMID 39267853, 2024). "Investigating the PTMs of Sp1 will contribute to a deeper understanding of the mechanism underlying the cell signaling pathway regulating Sp1 stability and the regulatory mechanism by which Sp1 affects cancer progression." (PMID 39228402, 2024). "Sp1 levels correlate with patient survival in almost all cancers, with high Sp1 levels associated with poor prognosis." (PMID 38540340, 2024). "There is a sub-set of miRNAs that directly inhibit Sp1 expression and the resulting inverse expression of these miRNAs with Sp1 is sometimes also associated with their use as a positive prognostic value for cancer patients." (PMID 36982239, 2023). "Understanding the relationship between EF24 and Sp1 ubiquitination is important because Sp1 is implicated in the transcription of genes involved in cancer progression." (PMID 38001739, 2023). "Specificity protein 1 (SP1) is associated with different types of cancer, neurological and cardiovascular disease and ZNF341 is involved in immune-mediated disorders and infection susceptibility by regulating IL-6 signaling." (PMID 36266402, 2022). "Future studies will attempt to establish a causative link between loss of Sp1 expression and aneuploidy in human cancers by determining if restoring Sp1 expression levels in primary patient samples can rescue chromosome segregation defects." (PMID 35916925, 2022). "Many human cancer cells exhibited higher levels of Sp1 expression, and the levels of Sp1 expression was associated with the state of a tumor and poor clinical prognosis." (PMID 35869499, 2022). "This is also consistent with the motif enrichment result that enriched TFs in the PRC2−-CGI class were strongly overlapped between different cancer types, and were associated with cell-cycle TFs, such as SP1, JUND, NFY, E2F4, and E2F1." (PMID 33931649, 2021).